RN7SKP241 (RN7SK pseudogene 241)
Gene: Miscellaneous RNA gene on chromosome 10 (24,908,522 to 24,908,812, reverse strand). Ensembl gene ENSG00000240294.
Homologues: Orthologues: chimpanzee 7SK (94% identical), mouse Gm56378 (67% identical), guinea pig 7SK (62% identical), guinea pig 7SK (52% identical). Paralogues in human: RN7SKP71 (77% identical), RN7SKP203 (76% identical), RN7SKP79 (76% identical), RN7SKP176 (75% identical), RN7SKP217 (75% identical), RN7SKP37 (75% identical), RN7SKP25 (75% identical), RN7SKP20 (74% identical), RN7SKP255 (74% identical), RN7SKP124 (74% identical), RN7SKP180 (74% identical), RN7SKP214 (74% identical), and 283 more.